NBDY (negative regulator of P-body association)
Description:
Promotes dispersal of P-body components and is likely to play a role in the mRNA decapping process.
Synonyms: LINC01420; NoBody
Gene: Protein-coding gene on chromosome X (56,729,219 to 56,819,179, forward strand). Ensembl gene ENSG00000204272.
Subcellular location: Cytoplasm, P-body
Gene Ontology:
Molecular function: protein binding
Biological process: negative regulation of cytoplasmic mRNA processing body assembly; nuclear-transcribed mRNA catabolic process
Cellular component: P-body
Homologues: Orthologues: chimpanzee NBDY (100% identical), mouse Nbdy (93% identical), pig NBDY (93% identical), dog NBDY (90% identical), guinea pig NBDY (85% identical).
Diseases named in the same sentence as NBDY in open-access papers:
NBDY is named in the same sentence as 6 diseases in open-access papers, as found by Europe PMC text mining. Sharing a sentence is not in itself a finding about the gene and the disease.
NBDY shares sentences with these, for which no sentence is quoted: cancer (3 papers); nasopharyngeal carcinoma (3); melanoma (1); pancreatic cancer (1); thyroid cancer (1); tumor (1).